OPN4 (opsin 4)
Description:
G protein-coupled photoreceptor that signals through the G(q/11) family of G proteins in response to light in intrinsically photosensitive retinal ganglion cells (ipRGCs) (By similarity). Can also activate other G proteins, including G(i/o) and G(s), depending on the cell type, leading to either activation or inhibition of adenylate cyclase and cAMP-dependent signaling. Activation occurs when opsin-bound cis-retinal chromophore absorbs a photon and isomerizes to all-trans-retinal, inducing a conformational change in the opsin that triggers a G protein-mediated phototransduction cascade. Acts as a bistable protein, allowing photoreversible regeneration of the cis-retinal chromophore after stimulation. Contributes to non-image-forming visual response to light in ipRGCs, including the pupillary light reflex and the regulation of circadian rhythms (By similarity). In M1 ipRGCs (non-image forming) subtypes, activates a G(q)-phospholipase C (PLC) signaling cascade leading to depolarization through opening of TRPC6/7 channels and decreased intrisic excitability (By similarity). Mediates phototransduction in M4 ipRGCs (image forming) subtypes across dim to bright light conditions via G(q)-PLC signaling, resulting in increased intrisic excitability through closure of potassium leak channels (most likely TASK channels), thereby enhancing contrast sensitivity (By similarity). At bright light intensities, further enhances depolarization in M4 ipRGCs via activation of TRPC channels (By similarity). May be involved in the optokinetic visual tracking response. May also play a role in regulating retinal hyaloid vessel growth and regression (By similarity). [Isoform 2]: In contrast with isoform 1, cannot activate G(i/o) and G(s) family of G proteins in response to light.
Synonyms: MOP; melanopsin
Tractability: Small molecule: it belongs to a druggable protein family. Antibody: its Gene Ontology location is reachable by antibodies, with high confidence; UniProt places it where antibodies can reach, with medium confidence; UniProt predicts a signal peptide or a membrane-spanning region.
Chemical probes: AA92593
Gene: Protein-coding gene on chromosome 10 (86,654,518 to 86,666,460, forward strand). Ensembl gene ENSG00000122375.
Subcellular location: Cell membrane; Cell projection, axon; Cell projection, dendrite; Perikaryon
Pathways (Reactome):
Signal Transduction: G alpha (q) signalling events; Opsins
Gene Ontology:
Molecular function: 11-cis retinal binding; G protein-coupled photoreceptor activity; G protein-coupled receptor activity; protein binding
Biological process: adenylate cyclase-activating G protein-coupled receptor signaling pathway; adenylate cyclase-inhibiting G protein-coupled receptor signaling pathway; phototransduction; cellular response to light stimulus; entrainment of circadian clock by photoperiod; G protein-coupled receptor signaling pathway; hyaloid vascular plexus regression; optokinetic behavior; phospholipase C-activating G protein-coupled receptor signaling pathway; regulation of circadian rhythm; visual perception; detection of visible light
Cellular component: plasma membrane; membrane; perikaryon; photoreceptor disc membrane; axon; dendrite; sperm head plasma membrane
Genetic constraint (gnomAD): Loss-of-function variants: 45 observed, 50.19 expected, observed/expected ratio (o/e) 0.9, 90% interval 0.7 to 1.15. The upper end of that interval is the gene's LOEUF score, 1.15, which puts it in group 5 of 6, group 1 being the genes least tolerant of losing a copy. Missense variants: 649 observed, 637.95 expected, observed/expected ratio (o/e) 1.02, 90% interval 0.95 to 1.09. Synonymous variants: 258 observed, 255.39 expected, observed/expected ratio (o/e) 1.01, 90% interval 0.91 to 1.12.
Homologues: Orthologues: chimpanzee OPN4 (97% identical), macaque OPN4 (96% identical), pig OPN4 (80% identical), rabbit OPN4 (79% identical), dog OPN4 (78% identical), mouse Opn4 (76% identical), rat Opn4 (76% identical), guinea pig OPN4 (75% identical), tropical clawed frog opn4 (59% identical), zebrafish opn4b (56% identical), zebrafish opn4a (56% identical), Drosophila melanogaster Rh2 (25% identical), and 4 more. Paralogues in human: OPN5 (20% identical), RHO (20% identical), OPN3 (19% identical), RRH (19% identical), OPN1SW (19% identical), OPN1MW (18% identical), OPN1MW2 (18% identical), OPN1MW3 (18% identical), OPN1LW (18% identical).